DIAPH1 (diaphanous related formin 1)
Diseases named in the same sentence as DIAPH1 in open-access papers (continued):
Sharing a sentence is not in itself a finding about the gene and the disease.
Hypertension (1 paper, 2020). The presence of chronic increased pressure in the systemic arterial system. "Association analyses of DIAPH1 SNPs with hypertension in the case-control study." (PMID 31899686, 2020). "In the case-control study of hypertension, the allele frequencies of the DIAPH1 rs3805691, rs251019, and rs11954998 SNPs in controls were consistent with Hardy-Weinberg equilibrium (HWE), whereas the allele frequencies of rs251018 and rs7703688 were not (HWEP = 0.004 and P < 0.001, respectively)." (PMID 31899686, 2020).
hypopharyngeal squamous cell carcinoma (1 paper, 2019). "Moreover, because different types of HNSCCs, such as LSCC and hypopharyngeal squamous cell carcinoma, have distinctively different biologic behaviours, we analysed GSE65858 dataset based on different primary sites and found the trend that high DIAPH1 expression was associated with poor OS in LSCC." (PMID 30733838, 2019).
intracerebral hemorrhage (1 paper, 2020). A cerebrovascular disorder characterized by bleeding into one or both cerebral hemispheres including the basal ganglia and the cerebral cortex. "Analysis for HS subtypes showed that compared to the TT/TC genotypes, the CC genotype of rs7703688 conferred higher risk for subarachnoid hemorrhage (SAH), whereas none of the DIAPH1 SNPs studied showed association with intracerebral hemorrhage (ICH)." (PMID 31899686, 2020).
laryngeal carcinoma (1 paper, 2022). Carcinoma that arises from the laryngeal epithelium. "DIAPH1 upregulation inhibits apoptosis in laryngeal carcinoma cells." (PMID 36589226, 2022).
lymph node metastasis (1 paper, 2021). "In the present study, IHC analysis of DIAPH1 revealed significant increases in DIAPH1 expression in the presence of factors associated with severe illness and short OS, such as high T stage, lymph node metastasis, high clinical stage, and primary supraglottic or subglottic tumors." (PMID 34631544, 2021). "IHC analysis of 126 patients showed that DIAPH1 protein expression was significantly upregulated in patients with high T stage, lymph node metastasis, later clinical-stage, or supraglottic or subglottic LSCC." (PMID 34631544, 2021).
morbid obesity (1 paper, 2021). An excess of body weight, normally defined as an individual with a body mass index greater than 35 or a body weight greater than one hundred percent of ideal body weight. "Our first hypothesis was that compared to obese subjects, AGER/DIAPH1 expression in adipose tissue would be significantly higher in subjects with morbid obesity whereas lower expression of mRNA transcripts encoding the AGE-detoxifier enzyme GLO1 was predicted in those individuals." (PMID 34103691, 2021).
myocardial infarction (1 paper, 2020). Gross necrosis of the myocardium, as a result of interruption of the blood supply to the area, as in coronary thrombosis. "DIAPH1 also play a role in signal transduction in smooth muscle cells, and DIAPH1 blockade could reduce cardiac muscle cell damage after myocardial infarction." (PMID 32349667, 2020).
myocardial ischemia (1 paper, 2020). A disorder of cardiac function caused by insufficient blood flow to the muscle tissue of the heart. "Importantly, animal experiments have demonstrated that genetic deletion of DIAPH1 led to infarct size reduction and improved contractile function after myocardial ischemia/reperfusion." (PMID 31899686, 2020). "Previous studies have identified an essential role for DIAPH1 in actin cytoskeletal remodeling, arterial SMC cell migration, and as a mediator of myocardial ischemia/reperfusion injury and vascular and neuroinflammatory dysfunction." (PMID 31899686, 2020).
Nijmegen breakage syndrome (1 paper, 2025). Nijmegen breakage syndrome is a rare genetic disease presenting at birth with microcephaly, dysmorphic facial features, becoming more noticeable with age, growth delay, and later-onset complications such as malignancies and infections. "Interestingly, patients with biallelic mutations in the actin nucleating factor DIAPH1 exhibit a striking overlap of clinical features with the HR deficiency disorders, Nijmegen Breakage Syndrome (NBS) and Warsaw Breakage Syndrome (WABS)." (PMID 40368919, 2025).
Parkinson disease (1 paper, 2025). A progressive degenerative disorder of the central nervous system characterized by loss of dopamine producing neurons in the substantia nigra and the presence of Lewy bodies in the substantia nigra and locus coeruleus. "Accumulating evidence implicates the RAGE and its obligatory signaling partner Diaph1 in the neuroinflammatory cascade that drives dopaminergic loss in Parkinson’s disease." (PMID 40981102, 2025).
small artery occlusion (1 paper, 2020). "DIAPH1 mRNA expression was compared between 66 IS [43 small artery occlusion (SAO) and 23 large-artery atherosclerosis (LAA)] and 58 controls." (PMID 31899686, 2020).
T-cell deficiency (1 paper, 2022). "Our results add evidence in support of the link between homozygous DIAPH1 loss and T-cell deficiency." (PMID 36212620, 2022).
type 1 diabetes (1 paper, 2025). "Global deletion of Diaph1 disrupts beta-actin polymerization in the sciatic nerve during type 1 diabetes." (PMID 41148850, 2025).
vascular malformation (1 paper, 2023). A non-neoplastic disorder that is the result of defects of vascular morphogenesis. "This includes some of the genes for moyamoya phenomenon, other vascular malformations, abnormalities of coagulation including CBL, DIAPH1, CHD4, CNOT3, and SETD5." (PMID 36253534, 2023).
tumor (23 papers, 2009 to 2025). "One candidate tumor suppressor on 5q is the mammalian Diaphanous (mDia)-related formin mDia1, encoded by DIAPH1 (5q31.3)." (PMID 19768111, 2009). "Based on this, one would predict that the HR deficiency in tumours arising as a consequence of DIAPH1 loss could be specifically targeted with therapeutic agents that exhibit synthetic lethality with an HR defect." (PMID 40368919, 2025). "Despite this, further work is needed to clarify whether DIAPH1 mutation or loss in tumours creates a genetic vulnerability that can be exploited therapeutically." (PMID 40368919, 2025). "Second, we analyzed clinical and mRNA expression data of 500 patients with HNSCC, from TCGA, and found that in class G3, high DIAPH1 expression was significantly associated with poor OS (p = 0.002) and that the expression of DIAPH1 was higher in tumor tissues than in adjacent normal tissues." (PMID 30733838, 2019). "The tumor weight of the NC group was significantly higher than that of the two DIAPH1-knockdown groups 21 d after transplant, suggesting that DIAPH1-knockdown suppresses tumor growth in NOD/SCID mice." (PMID 34631544, 2021). "Using 36 paired LSCC and matching adjacent non-tumor tissues, we previously showed that expression of the protein diaphanous related formin 1 (DIAPH1, also termed mDia1), a member of the formin family, is significantly upregulated in LSCC tissues." (PMID 34631544, 2021). "Significantly more rapid tumor growth occurred in the NC group than in the two DIAPH1-knockdown groups." (PMID 34631544, 2021). "In immune-cells these activities are required for cell motility during defense of infection and also tumor cells with ectopic expression of DIAPH1 show increased cell motility and invasion." (PMID 26124177, 2015). "Since adhesion to the substrate is one of the earliest steps of tumor cell metastasis, we analyzed the effect of DIAPH1-depletion on early cell adhesion on collagen (two hours after seeding) of non-stimulated HCT-116 cells." (PMID 26124177, 2015). "DIAPH1-deficient mice (in mice defined as mDia1) develop age-dependent myeloproliferative or myelodysplastic phenotypes, suggesting that DIAPH1 may act as a tumor suppressor." (PMID 41440765, 2025). "However, previous research on the role of Diaph1 in cell migration mainly focused on tumor cells and nerve cells." (PMID 39010074, 2024). "Interestingly, although DIAPH1 is upregulated in many types of tumors and promotes tumor cell proliferation, migration, invasion, progression in vivo, it also suppresses apoptosis, the relationship between DIAPH1 and survival is inconsistent." (PMID 34631544, 2021). "Due to the change of tumor characteristics and the expression of DIAPH1 caused by chemoradiotherapy, only the patients without chemoradiotherapy experiences were included." (PMID 34631544, 2021). "Abnormal expression of DIAPH1 can lead to abnormalities in stress fibers, pseudopodia, and microtubules of tumor cells, which influences proliferation, adhesion, and migration of tumor cells, potentially changing the course of the tumor." (PMID 34631544, 2021). "LPA-stimulation may enhance this effect by additionally activating the actin nucleating activity of DIAPH1 to stimulate formation of cellular protrusion required for tumor cell invasion." (PMID 26124177, 2015). "Therefore, we hypothesized that, in LSCC, a type of HNSCC, DIAPH1 may also influence tumorigenesis and tumor development through interfering with the apoptosis of tumor cells." (PMID 30733838, 2019). "The expression levels of DIAPH1, DIAPH2, and DIAPH3 in PAAD tumor tissues were significantly higher than in normal tissues in the consensus databases of TCGA and GTEx." (PMID 36589226, 2022). "The IHC data demonstrated that DIAPH1 and DIAPH3 expression were higher in tumor tissue when compared to adjacent normal tissue, and DIAPH2 was positively expressed in pancreatic acinar cells in adjacent normal tissue but not pancreatic ductal cells." (PMID 36589226, 2022).
tumor (continued). "Additionally, short-term MITF depletion downregulates the diaphanous-related formin 1 (DIA1), leading to a p27-dependent cell cycle arrest and increases rho-associated coiled-coil containing protein kinase (ROCK)-dependent invasiveness of the cells, indicating a tumor-promoting role of MITF." (PMID 34071193, 2021). "Notably, the expression levels of DIAPH1, DIAPH2, and DIAPH3 were significantly higher in PAAD tumor tissues than in normal tissues." (PMID 36589226, 2022). "Mammals possess three members of this protein family, diaphanous homolog 1 (DIAPH1), DIAPH2, and DIAPH3, which have been implicated in both normal cell physiology and tumor progression." (PMID 36589226, 2022). "We confirmed an aberrant increase of cassette exon skipping in tumor specimens for PACSIN2 exon 8, DIAPH1 exon 2, FGFR1OP2 exon 4, MARK3 exon 16, DST exon 93, LMO7 exon 10, and RBM5 exon 7, whereas ADD3 exon 13, MAP3K7 exon 12, and MARK2 exon 15 were preferentially included in tumor specimens." (PMID 34202984, 2021). "However, we focused our attention on PACSIN2, DIAPH1, MARK3, ADD3, MAP3K7, and MARK2 cassette exons as these events were validated in both normal and cancer cell lines and in non-pathological and tumor breast specimens." (PMID 34202984, 2021).
cancer (16 papers, 2012 to 2024). A tumor composed of atypical neoplastic, often pleomorphic cells that invade other tissues. "KEGG pathway analysis further suggested that the “adherens junction” and “proteoglycans in cancer” may be potential mechanisms underlying the effect of DIAPH1 on PAAD carcinogenesis." (PMID 36589226, 2022). "Diaph1 is engaged in the proper organization of actin cytoskeletal dynamics, which is crucial in cancer invasion, metastasis, angiogenesis, and axonogenesis." (PMID 39335163, 2024). "Although the biological functions of DIAPH1 have been widely studied, its biological and clinical significance in cancer, especially in LSCC, remains poorly understood." (PMID 30733838, 2019). "To date, there is very limited knowledge on the role of Diaph1 in the progression of cancer." (PMID 39335163, 2024). "Diaph1 and cytoskeletal proteins may regulate cancer cell growth and invasion by the remodeling of the actin cytoskeleton." (PMID 39335163, 2024). "In addition, the corresponding heatmap data in pan-cancer showed a significant positive correlation between DIAPH1 and the four intersecting genes in most cancer types in TCGA cohort." (PMID 36589226, 2022). "In contrast to Diaph1, the relevance of Diaph2 in cancer progression has been less investigated." (PMID 30926831, 2019). "However, the most recent evidence indicates that Diaph1 may play a crucial role in cancer with accompanied inflammation and oxidative stress." (PMID 39335163, 2024). "Of particular interest is the interaction between diaphanous-related formin 1 (Diaph1) and RAGE during the progression of human cancers." (PMID 39335163, 2024). "Thus we hypothesized that DIAPH1 participates in progression of cancers by virtue of its regulatory role in the cell cycle and sought to elicit the specific regulatory interactions mediated by DIAPH1 that are associated with development and progression of LSCC." (PMID 34631544, 2021).
infection (10 papers, 2014 to 2024). The state of being infected such as from the introduction of a foreign agent such as serum, vaccine, antigenic substance or organism. "Recent findings have expanded the clinical phenotype of DIAPH1 deficiency to include severe susceptibility to infections, placing this monogenic disease amongst the etiologies of inborn errors of immunity." (PMID 39076976, 2024). "We report the case of an infant presenting with inflammatory enteropathy, without any initial infections and without seizures, in whom we found a novel bi-allelic DIAPH1 mutation." (PMID 39076976, 2024). "Furthermore, the mammalian Diaphanous-related formin-1 (mDia1) has been shown to control cytoskeleton dynamics during human influenza A virus infection, playing a role in restricting infection initiation." (PMID 38338917, 2024). "The knockdown of DIAPH1 or DIAPH2 strongly reduced HIV-1 entry, an effect mimicked by SMIFH2, HIV-1-induced MT stabilization, and HIV-1 reverse transcription during early stages of infection." (PMID 37240404, 2023). "Conversely, the infection of non-human retroviruses such as Simian Immunodeficiency Virus and Murine Leukemia Virus was independent of them and did not result in MT stabilization, showing the functional specificity of DIAPH1 or DIAPH2 in HIV-1 infection." (PMID 37240404, 2023).
metabolic disorders (3 papers, 2020 to 2022). "Studies both from human subjects and animal models are presented to highlight the breadth of evidence linking RAGE and DIAPH1 to the cardiovascular consequences of these metabolic disorders." (PMID 32211423, 2020). "This relationship might suggest a protective role of reduced DIAPH1 levels in PCOS patients, which also displays the complexity of PCOS, a syndrome of metabolic disorders and hormone dysregulation." (PMID 35185386, 2022).
neurodegenerative disease (3 papers, 2021 to 2025). A disorder of the central nervous system characterized by gradual and progressive loss of neural tissue and neurologic function. "Recent studies have shown that in animal models of neurodegenerative diseases, the pharmacological or genetic blocking of Diaph1 attenuates inflammation and Diaph1-associated perturbations." (PMID 39335163, 2024). "In this section, we delve into how RAGE, Diaph1, and associated ligands show altered expression in ALS and similar neurodegenerative diseases, drawing on transcriptomic, in vitro and in vivo, and proteomic evidence, with a focus on recent developments." (PMID 40981102, 2025).
cardiovascular disease (2 papers, 2022 to 2023). "This Review focuses on RAGE/DIAPH1 and its role in perturbation of metabolism and processes that converge to augur cardiovascular disease." (PMID 35811725, 2022).
Neurological Disease (2 papers, 2009 to 2024). "Altogether, data obtained from expression patterns of DIAPH1 and pathogenic variants in this gene in two diseases show that DIAPH1 has a crucial role in brain development, and a defect in this gene may cause a neurological disorder." (PMID 39578953, 2024).
DIAPH1 also shares sentences with these, for which no sentence is quoted: auditory neuropathy (3 papers); endothelial dysfunction (3); leukemia (3); viral infection (3); anemia (2); cyst (2); diabetic neuropathy (2); Hearing impairment (2); Hydrocephalus (2); liver cancer (2); lymphopenia (2); Myelodysplasia (2); Nephropathy (2); neutropenia (2); oral squamous cell carcinoma (2); peripheral neuropathy (2); primary immunodeficiency (2); Seizure (2); acute lymphoblastic leukemia (1); acute myeloid leukemia (1); adenoma (1); amyotrophic lateral sclerosis (1); autosomal dominant non-syndromic hearing loss 1 (1); Bacterial infection (1); Blau syndrome (1); Blindness (1); bone marrow disease (1); breast tumor (1); cardiac hypertrophy (1); cardiomyopathy (1).
A further 33 diseases each share a sentence with DIAPH1 in 1 paper.